IL6 (interleukin 6)
Diseases named in the same sentence as IL6 in open-access papers (continued):
Sharing a sentence is not in itself a finding about the gene and the disease.
sarcopenia (continued). "In sarcopenia, pro-inflammatory myokines such as IL-6 and TNF-α are persistently overexpressed, activating the JAK/STAT and NF-κB signaling pathways, which induce and maintain a chronic low-grade inflammatory state." (PMID 41140691, 2025). "Butyrate potently antagonizes chronic, low-grade inflammation, a key driver of sarcopenia, by inhibiting the NF-κB pathway and subsequent production of pro-inflammatory cytokines such as IL-6." (PMID 41480113, 2025). "Multivariable logistic regression analysis indicated that patients in the sarcopenia group were positively correlated with interleukin (IL)-6 and tumour necrosis factor (TNF)-α (P<0.05)." (PMID 40265008, 2025). "Increased IL-6 levels in metastatic cancers also contribute to cancer-related cachexia, malnutrition, and sarcopenia." (PMID 40004836, 2025). "The available reports on changes in concentrations of CRP, IL-1β, IL-6 and TNFα confirmed that inflammation was a critical component of sarcopenia progression." (PMID 41345186, 2025). "Pro-inflammatory cytokines like TNF-α and IL-6, released by adipose tissue, impair muscle protein synthesis while enhancing lipogenesis, promoting both sarcopenia and fat accumulation." (PMID 40251227, 2025). "In univariate logistic regression, high IL‐6 was found to be a predictor of sarcopenia (OR 2.32, 95%CI 1.18–4.54, p = 0.02)." (PMID 41380167, 2025). "Future research should compare these indices with other emerging sarcopenia biomarkers (e.g., myostatin, IL-6), or consider combining them into composite indices." (PMID 40712242, 2025). "Pulmonary impairment is also often associated with elevated pro-inflammatory cytokines, such as IL-6 and TNF-α, which have been implicated in the pathogenesis of sarcopenia." (PMID 40712241, 2025). "Our findings demonstrate that elevated preoperative serum levels of IL‐6 and GDF‐15 are closely associated with the presence of sarcopenia, adverse pathological features and diminished survival outcomes in patients undergoing RC for BC." (PMID 41380167, 2025). "Certain inflammatory pathways involve substances like IL-6 and TNF are implicated in both sarcopenia and OSA." (PMID 40055243, 2025). "The specific increase in TNF-α in sarcopenia and the refined IL-6 levels after excluding studies with significant heterogeneity delineate the muscle-autonomous inflammatory pathway." (PMID 40507924, 2025). "Excluding these two studies from the meta-analysis significantly reduced heterogeneity (I2 = 38.0%), and a significant positive correlation between IL-6 and sarcopenia was found (SMD = 0.16, 95% CI (0.05, 0.28), K = 15, N = 2502, I2 = 38%)." (PMID 40507924, 2025). "The observed correlation between high IL‐6 levels and sarcopenia aligns with the existing literature." (PMID 41380167, 2025). "In turn, the abnormal release of several of these pro-inflammatory cytokines and chemokines, including IL-6, TNF-α, and CXCL10, has been independently associated with frailty and sarcopenia." (PMID 40805993, 2025). "Studies to date have explored the relationship between Single Nucleotide Polymorphisms (SNPs) and sarcopenia, focusing on vitamin D receptor (VDR), interleukin-6 (IL6), alpha-actinin-3 (ACTN3), and Myostatin (MSTN) polymorphisms." (PMID 40772803, 2025). "These markers are strongly linked to age-related morbidity and mortality: elevated CRP predicts CVD onset in older adults, and TNF-α/IL-6 correlate with sarcopenia and disability." (PMID 41561801, 2025). "Future research should focus on elucidating the precise molecular mechanisms underlying IL‐6 and GDF‐15‐mediated sarcopenia and evaluating the efficacy of targeted therapies in clinical trials." (PMID 41380167, 2025). "This complex regulatory relationship positions IL-6 as an emerging therapeutic target for sarcopenia, highlighting the importance of personalized interventions." (PMID 41140691, 2025). "Levels of inflammatory biomarkers like tumor necrosis factor α and interleukin 6 are relevant to frailty/sarcopenia." (PMID 40989160, 2025).
sarcopenia (continued). "Elevated levels of adipokines, such as leptin and interleukin-6, can impair muscle function and contribute to the progression of sarcopenia." (PMID 41403750, 2025). "Studies have shown that IL-6 levels correlate with muscle wasting and atrophy, which are key features of sarcopenia." (PMID 40740773, 2025). "K/BxN seems to be an excellent choice for investigating systemic correlation between inflammatory mediators (particularly high circulating IL-6) and sarcopenia, or for examining treatments focused on systemic myositis and associated muscle fibrosis." (PMID 41267875, 2025). "This is distinct from the persistently elevated IL-6 observed in sarcopenia and metabolic diseases, which activates NF-κB, contributing to muscle atrophy." (PMID 41441428, 2025). "Patients with sarcopenia exhibited increased concentrations of IL-6 and a significant decrease in NK cell counts, indicating a potential impairment in immune function." (PMID 40740773, 2025). "On one hand, cancer induces sarcopenia through mechanisms such as systemic inflammation, metabolic dysregulation, elevated catabolic cytokines (e.g., IL-6, TNF-α), and the direct myotoxic effects of chemotherapy and radiotherapy." (PMID 40661078, 2025). "Instead, specific increases in TNF- α and IL-6 in sarcopenia levels reflect a muscle-autonomous inflammatory pathway." (PMID 41226798, 2025). "In detail, patients with PACS are exposed to high systemic levels of sarcopenic cytokines, namely IL-6 and TNFα, which reduce the number and functionality of mitochondria in skeletal muscle cells, inducing sarcopenia." (PMID 39200115, 2024). "Therefore, the aim of this study was to comprehensively investigate the causal relation for IL-6 or sIL6 with sarcopenia using a two-sample Mendelian randomization approach, and to determine whether targeting these factors may be a viable approach to preventing or treating muscle loss." (PMID 38750566, 2024). "As IL6 is also a myokine secreted by muscle cells, a reverse MR analysis was performed to identify the effect of sarcopenia traits on interleukin." (PMID 38750566, 2024). "Previous study also confirmed that sarcopenia was associated with systemic inflammation as evidenced by elevated levels of TNF-α and IL-6." (PMID 38411849, 2024). "Increased levels of IL-6 were also found in older patients with sarcopenia (depending on the severity of sarcopenia)." (PMID 38375321, 2024). "The pro-inflammatory cytokines (such as interleukin-6 and TNF-α) produced during RA development are associated with proteolysis and resting energy expenditure, which are contributors to sarcopenia." (PMID 38638121, 2024). "The expression of proinflammatory factors in the SASP is an important factor in sarcopenia, and the overexpression of IL-6 can significantly lead to muscle atrophy in mice." (PMID 38774874, 2024). "A notable number of epidemiological studies have established a direct correlation between persistently high levels of serum IL-6 and frailty, indicating that increased IL-6 levels are a harbinger of the development of sarcopenia." (PMID 38892810, 2024). "It was found that patients with sarcopenia have increased pro-inflammatory cytokine levels (interleukin-6, tumor necrosis factor α (TNFα)), C-reactive protein, and decreased levels of anti-inflammatory cytokine interleukin-10." (PMID 38505257, 2024). "The TNF‐ɑ, IL‐6, and IL‐8 levels of 40 sarcopenia patients were stratified according to the quartiles." (PMID 38270306, 2024). "Pro-inflammatory cytokines, such as IL6 and IL1β, contribute significantly to the phenomenon of inflammation, both during sarcopenia and osteoporosis, also enhancing PGE2." (PMID 38892069, 2024). "It has also been reported that older people with sarcopenia show significantly higher levels of circulating IL-6 and TNF-α and that high levels of IL-6 and CRP increase the risk of loss of muscle strength." (PMID 39203857, 2024).
sarcopenia (continued). "Chronic inflammation also plays an important role in the development of sarcopenia, such as increased level of TGF-βand IL-6, which is a cause of muscle atrophy." (PMID 38797769, 2024). "Inflammatory markers, such as tumor necrosis factor (TNF) and interleukin-6 (IL-6), as well as testosterone and growth hormones, have been identified for sarcopenia diagnosis." (PMID 38337720, 2024). "Lin also showed that people with COPD had significantly higher concentrations of the inflammatory factors IL-6 and IL-10, leading to increased degradation of muscle proteins and decreased muscle tissue, which exacerbated sarcopenia." (PMID 38635756, 2024). "The level of circulating pro-inflammatory cytokines (interleukin (IL)-6, tumor necrosis factor (TNF) or IL-1β) is a risk factor in cardiovascular and neurodegenerative diseases and is also associated with sarcopenia and frailties." (PMID 38495887, 2024). "Inflammation in particular has been linked to the development of sarcopenia, with data showing that individuals with sarcopenia have higher levels of circulating TNF-α and interleukin (IL)-6." (PMID 38911683, 2024). "In the context of aging inflammation, prolonged exposure to IL-6 signaling is involved in the pathogenesis of sarcopenia." (PMID 38525752, 2024). "In this study, the binning method was used to stratify the levels of TNF‐ɑ, IL‐6, and IL‐8 in 40 sarcopenia patients in quartiles." (PMID 38270306, 2024). "Numerous clinical and epidemiological studies have shown that various plasma inflammatory markers, including CRP, high-sensitivity C-reactive protein, and interleukin-6, are often elevated in patients with sarcopenia and correlate with their prognosis." (PMID 38638440, 2024). "In conclusion, this study demonstrates that a 2-week intervention with Ophiocephalus striatus extracts reduces serum IL-6 levels in older adults with sarcopenia." (PMID 38525752, 2024). "This study demonstrated that a 2-week intervention with Ophiocephalus striatus extract positively impacted the serum IL-6 levels in older adults with sarcopenia." (PMID 38525752, 2024). "This study aimed to investigate the effects of Ophiocephalus striatus extract on insulin-like growth factor-1 serum, interleukin-6 serum levels, and sarcopenia-related parameters in older adults with sarcopenia." (PMID 38525752, 2024). "Elevated levels of IL-6, IL-1β, TNF-α, and C-reactive protein (CRP) have been implicated in the loss of muscle mass and strength in sarcopenia." (PMID 39101140, 2024). "Both inflammaging and altered renal function upregulate proinflammatory pathways leading to increased production of IL-6, which is a marker of sarcopenia." (PMID 39055699, 2024). "The positive impact of the Ophiocephalus striatus extract treatment on IL-6 serum levels in older adults with sarcopenia is possible because of its high protein and albumin content." (PMID 38525752, 2024). "Studies have shown a correlation between IL-6 levels and the severity of sarcopenia, age, and comorbidities in the elderly." (PMID 38525752, 2024). "Studies have shown that several cytokines (TNF-α, CRP, and IL-6) play an important role in the pathogenesis of sarcopenia." (PMID 38397848, 2024). "IL-6 is a very well-known pro-inflammatory cytokine closely related to skeletal muscle weakness in the elderly with sarcopenia." (PMID 38338718, 2024). "Second, proinflammatory mediators such as tumor necrosis factor-α and interleukin-6 play a pivotal role in the development and progression of sarcopenia." (PMID 36776611, 2023). "In a similar study, an increase in IL-6 and TNF-α was associated with poor exercise practice and nutritional habits in people with sarcopenia." (PMID 36831134, 2023). "Univariate logistic regression between sarcopenia and log (IL-6) showed a significant odds ratio (OR 14.88, p = 0.044) with an AUC of 0.72." (PMID 37173873, 2023).
sarcopenia (continued). "For instance, research examining the relationship between older adults sarcopenia and inflammatory factors revealed that patients with sarcopenia had significantly increased circulating concentrations of IL-6 and TNFα." (PMID 38235492, 2023). "Previous epidemiological studies have shown that patients with sarcopenic obesity have higher levels of cytokines, such as C-reactive protein (CRP), interleukin-6 (IL-6), and monocyte chemotactic protein-1 than those with sarcopenia." (PMID 36895276, 2023). "According to subgroup analysis, whey protein led to a statistically significant decrease in circulating IL-6 levels in individuals with sarcopenia and pre-frailty (MD: −0·98, 95 % CI: −1·56, −0·39, I2 = 0 %)." (PMID 35706399, 2023). "Elevated levels of inflammatory cytokines, such as IL-6 or TNF-alpha, have been associated with muscle wasting and increased risk of sarcopenia." (PMID 36984525, 2023). "Na análise univariada, a sarcopenia foi associada aos níveis séricos de IL-6 (p <0,001), assim como foram os resultados do teste de caminhada de 6 minutos (p = 0,012) ( Tabela 3 )." (PMID 37556651, 2023). "After accounting for potential confounding factors through adjustment, the presence of sarcopenia was found to have a positive correlation with IL-6." (PMID 38032288, 2023). "Subgroup analysis based on age (< 60 years) revealed a significant reduction of serum TNF-α following whey protein consumption, while subgroup analysis accounting for sarcopenia and pre-frailty status also exhibited a significant reduction of serum IL-6." (PMID 35706399, 2023). "Depois de normalizar em relação à idade, etnia, IMC, FEVE, e o uso de inibidores da enzima conversora de angiotensina/bloqueadores de receptor de angiotensina, a sarcopenia foi associada a níveis séricos de IL-6 mais altos e capacidade funcional pior." (PMID 37556651, 2023). "According to several horizontal and longitudinal studies, sarcopenia is associated with high levels of proinflammatory cytokines, including tumor necrosis factor-α (TNF-α), interleukin-6 (IL-6), and C-reactive protein (CRP)." (PMID 38260146, 2023). "Previous studies have shown that pro-inflammatory biomarkers, including IL-6, IL-10, IL-8, IL-15, CRP, TNF-α, and GDF-15, are associated with skeletal muscle decline and sarcopenia." (PMID 38026977, 2023). "Serum IL-10 levels were reduced in patients with sarcopenia, and the sarcopenia severity correlated positively with IL-6 and TNF-α levels." (PMID 37962457, 2023). "A notable discovery has been made regarding the reduction of TNF-α, IL-1β, and IL-6 levels following exercise and nutritional support in individuals diagnosed with sarcopenia." (PMID 38032288, 2023). "Simultaneously, the reduction of anti-inflammatory microorganisms such as Akkermannia in the gut causes overproduction of several cytokines in patients with cirrhosis, most of which have been demonstrated to be correlated with sarcopenia, such as IL-6 and CRP." (PMID 37881635, 2023). "Em suma, este estudo demonstrou que a sarcopenia é altamente prevalente e está associada a níveis mais elevados de IL-6 e redução da capacidade funcional (de acordo com o teste da caminhada de 6 minutos) em pacientes idosos com IC." (PMID 37556651, 2023). "Even though we did not record such differences, we observed the trend toward higher IL-6 values in the sarcopenia group." (PMID 37465171, 2023). "In males, however, the OR for sarcopenia was significantly higher for IL-6 levels lower than 150 pg/mL (OR: 0.18, 95% CI: 0.04, 0.81, p = 0.031)." (PMID 37630720, 2023). "In our clinical indicators, we also found a positive correlation between the inflammation-related index IL-6 and the upregulation of bacteria and metabolites in the sarcopenia group." (PMID 38026977, 2023). "Using Spearman’s test, IL-6 and sarcopenia had a p-value = 0.014; CP and sarcopenia has a p = 0.057, while IL-6 and CP had a p = 0.007." (PMID 37173873, 2023).
sarcopenia (continued). "The correlation between sarcopenia and IL-6 has already been described for several types of cancer, suggesting that IL-6 is a central regulator of cancer progression and cancer-associated cachexia." (PMID 37173873, 2023). "Os principais achados deste estudo referem-se à associação entre sarcopenia e níveis séricos de IL-6, bem como com a capacidade funcional em pacientes idosos com IC ( Figura central )." (PMID 37556651, 2023). "Adipose tissue is a significant source of proinflammatory cytokines, such as IL-1β and IL-6, both probably involved in the development of sarcopenia, and TNF-α." (PMID 37373124, 2023). "Some studies have indicated higher levels of pro-inflammatory cytokines, such as tumor necrosis factor (TNF)-α and interleukin (IL)-6, in individuals with sarcopenia." (PMID 38032288, 2023). "No modelo multivariado 1, após padronização para idade, IMC, etnia, FEVE e uso de IECA/BRA, a IL-6 permaneceu associada à sarcopenia: para cada aumento de 1 pg/mL na IL-6, houve um aumento de 10% na prevalência de sarcopenia." (PMID 37556651, 2023). "Another interesting finding is that IL-6 emerges for the first time as a potential specific marker of sarcopenia in HCC cirrhotic patients (VIF = 1; OR 14.8, p = 0.04)." (PMID 37173873, 2023). "Univariate logistic regression between sarcopenia and log (IL-6) showed a statistically significant odds ratio (OR 14.88, p = 0.044) with an AUC of 0.72, a sensibility of 0.72 and a specificity of 0.57." (PMID 37173873, 2023). "Skeletal muscle tissue produces myokines, such as interleukin (IL)-6, IL-15, tumor necrosis factor-α, and transforming growth factor-β, and altered myokine activity can induce immune senescence in sarcopenia." (PMID 37958368, 2023). "Multiple studies have shown that sarcopenia is associated with a significant increase in pro-inflammatory cytokines, including TNF-α, IL-6, and C-reactive protein." (PMID 36002808, 2022). "It has been shown that elevation of IL-6 and CRP especially play a role as a possible inflammatory link between sarcopenia and cardiovascular risk." (PMID 35682063, 2022). "The mean age, MELD score, TBIL, INR, and proportions of patients with sarcopenia and more than one complication were higher in the progression group, and the increase in IL-6 was close to statistically significant." (PMID 35771410, 2022). "More specifically, a variety of cytokines, including tumor necrosis factor (TNF)-α, interleukin (IL)-1, IL-2, IL-4, IL-6, IL-8, and IL-10 play a role in the development of sarcopenia." (PMID 36160136, 2022). "Inflammatory cytokines, including pro-inflammatory and anti-inflammatory cytokines interleukin 6 (IL-6) and tumor necrosis factor alpha (TNF-α), have been repeatedly proved to be closely associated with sarcopenia in humans and animals." (PMID 36111339, 2022). "In this context, circulating IL6 and RCP levels have been described as sarcopenia-associated inflammatory markers, and are included in the GLIM criteria for the diagnosis of malnutrition." (PMID 35158762, 2022). "A positive association was found between the high level of IL-6, IL-17A, and TNF-α and the prevalence of sarcopenia for both men and women." (PMID 35237317, 2022). "The multivariate model demonstrates that an increase in one-unit PhA was related to 63.6% reduction [Prevalence ratio (PR) = 0.364] in the PR for sarcopenia, while an increment of 1 unit in IL-6 levels would increase the PR for sarcopenia by 0.6% (PR = 1.006)." (PMID 35463026, 2022). "In this way, we suggest that further studies should be performed to better understand the role of PhA, IL-6 and creatinine levels in the diagnosis and management of sarcopenia in the ND-CKD population." (PMID 35463026, 2022). "In older people with sarcopenia, high levels of IL-6 and soluble tumor necrosis factor receptor 2 (sTNFr2) were reported." (PMID 36498747, 2022).